SMNDC1 (survival motor neuron domain containing 1)
Description:
Involved in spliceosome assembly.
Synonyms: SMNR; SPF30; TDRD16C
Tractability: Small molecule: a structure with a bound ligand is known. PROTAC: ubiquitination databases record sites on it; its protein half-life has been measured.
Target class: Methyl-lysine/arginine binding protein; Reader; Epigenetic regulator; Tudor domain
Gene: Protein-coding gene on chromosome 10 (110,290,730 to 110,304,963, reverse strand). Ensembl gene ENSG00000119953.
Subcellular location: Nucleus speckle; Nucleus, Cajal body
Subcellular location (Human Protein Atlas): Nucleoplasm; Nuclear bodies
Pathways (Reactome):
Metabolism of RNA: mRNA Polyadenylation; mRNA Splicing - Major Pathway
Chromatin organization: CHD1 and CHD2 subfamily
Disease: Dengue Virus-Host Interactions
Gene Ontology:
Molecular function: protein binding; RNA binding
Biological process: apoptotic process; RNA splicing, via transesterification reactions; mRNA processing
Cellular component: nuclear body; nuclear speck; nucleoplasm; nucleus; Cajal body; cytoplasm
Genetic constraint (gnomAD): Loss-of-function variants: 3 observed, 20.82 expected, observed/expected ratio (o/e) 0.14, 90% interval 0.065 to 0.37. The upper end of that interval is the gene's LOEUF score, 0.37, which puts it in group 1 of 6, group 1 being the genes least tolerant of losing a copy. Missense variants: 124 observed, 210.54 expected, observed/expected ratio (o/e) 0.59, 90% interval 0.51 to 0.68. Synonymous variants: 62 observed, 73.04 expected, observed/expected ratio (o/e) 0.85, 90% interval 0.69 to 1.05.
Homologues: Orthologues: chimpanzee SMNDC1 (99% identical), dog SMNDC1 (99% identical), macaque SMNDC1 (99% identical), mouse Smndc1 (99% identical), pig SMNDC1 (99% identical), guinea pig SMNDC1 (99% identical), rabbit SMNDC1 (99% identical), tropical clawed frog smndc1 (89% identical), rat Smndc1 (84% identical), zebrafish smndc1 (79% identical), Drosophila melanogaster Spf30 (45% identical), Caenorhabditis elegans smr-1 (34% identical). Paralogues in human: SMN1 (24% identical), SMN2 (24% identical).
Diseases named in the same sentence as SMNDC1 in open-access papers:
SMNDC1 is named in the same sentence as 5 diseases in open-access papers, as found by Europe PMC text mining. Sharing a sentence is not in itself a finding about the gene and the disease. The quoted sentences say what the papers report.
hepatocellular carcinoma (1 paper, 2023). A malignant tumor that arises from hepatocytes. "SMNDC1 knock-down led to decreased proliferation and migration of hepatocellular carcinoma cells, establishing SMNDC1 as a potential therapeutic target." (PMID 37587144, 2023). "SMNDC1 further is essential for cell proliferation in different contexts, and a recent study reported worse survival in hepatocellular carcinoma patients with high SMNDC110." (PMID 37587144, 2023).
ovarian carcinoma (1 paper, 2022). A malignant neoplasm originating from the surface ovarian epithelium. "It has been reported that silencing SMNDC1 can significantly inhibit the proliferation of ovarian cancer cells, whereas the mechanism in ovarian cancer and the roles of SMNDC1 in other tumors have not been elucidated." (PMID 36263018, 2022).
Stroke (1 paper, 2025). Sudden impairment of blood flow to a part of the brain due to occlusion or rupture of an artery to the brain. "Lastly, SMNDC1 and IVD, although less characterized in stroke, were among the top IS-overexpressed proteins; their roles in RNA processing and mitochondrial metabolism suggest responses to ischemia-induced stress and energy deficits." (PMID 41152969, 2025).
tumour (3 papers, 2012 to 2022). "SMNDC1 was identified as an ideal marker predicting poor prognosis in LUAD in our study, as it was upregulated in tumor samples and in high-risk LUAD populations." (PMID 36263018, 2022).
cancer (2 papers, 2024 to 2025). A tumor composed of atypical neoplastic, often pleomorphic cells that invade other tissues. "Similarly, the key genes SNW1, SENP2 and SMNDC1 identified in this study in the context of acquired resistance, have previously been implicated in cancer cell proliferation, death, and metastasis, although their specific role in regulating platinum resistance remains unknown." (PMID 38957470, 2024). "While DDX46 functions as an RNA splicing factor similar to DDX42, detailed reports on the biological functions of SMNDC1 and UNK in cancer are currently limited." (PMID 40831000, 2025).